KRT5 (keratin 5)
Description:
Structural component of intermediate filaments in basal keratinocytes of stratified epithelia. Together with its obligate type I partner KRT14, contributes to the formation of the keratin intermediate filament network that provides mechanical stability and resilience to the basal layer of the epidermis. Regulates the recruitment of Langerhans cells to the epidermis, potentially by modulation of the abundance of macrophage chemotactic cytokines, macrophage inflammatory cytokines and CTNND1 localization in keratinocytes (By similarity).
Synonyms: CK-5; K5; KRT5A; CK5; DDD; DDD1; EBS1; EBS2; EBS2A; EBS2B; EBS2C; EBS2D; EBS2E; EBS2F
Tractability: PROTAC: ubiquitination databases record sites on it.
Gene: Protein-coding gene on chromosome 12 (52,514,575 to 52,520,530, reverse strand). Ensembl gene ENSG00000186081.
Subcellular location: Cytoplasm
Subcellular location (Human Protein Atlas): Intermediate filaments
Pathways (Reactome):
Developmental Biology: Developmental Lineage of Mammary Gland Luminal Epithelial Cells; Developmental Lineage of Mammary Gland Myoepithelial Cells; Developmental Lineage of Mammary Stem Cells; Differentiation of Keratinocytes in Interfollicular Epidermis in Mammalian Skin; Formation of the cornified envelope; Keratinization
Cell-Cell communication: Type I hemidesmosome assembly
Gene Ontology:
Molecular function: protein binding; scaffold protein binding; structural constituent of cytoskeleton; structural constituent of skin epidermis
Biological process: epidermis development; intermediate filament organization; intermediate filament polymerization; keratinization; regulation of cell migration; regulation of protein localization; response to mechanical stimulus
Cellular component: cytoplasm; extracellular exosome; intermediate filament; keratin filament; membrane; nucleus; protein-containing complex; cytosol
Genetic constraint (gnomAD): Loss-of-function variants: 16 observed, 45.17 expected, observed/expected ratio (o/e) 0.35, 90% interval 0.24 to 0.54. The upper end of that interval is the gene's LOEUF score, 0.54, which puts it in group 2 of 6, group 1 being the genes least tolerant of losing a copy. Missense variants: 724 observed, 801.81 expected, observed/expected ratio (o/e) 0.9, 90% interval 0.85 to 0.96. Synonymous variants: 323 observed, 321.48 expected, observed/expected ratio (o/e) 1, 90% interval 0.92 to 1.1.
Homologues: Orthologues: chimpanzee KRT6A (99% identical), macaque KRT5 (99% identical), pig KRT5 (95% identical), rabbit KRT5 (92% identical), guinea pig KRT5 (89% identical), mouse Krt5 (88% identical), rat Krt5 (88% identical), mouse Gm5478 (59% identical). Paralogues in human: KRT6A (76% identical), KRT6B (76% identical), KRT6C (76% identical), KRT75 (74% identical), KRT3 (65% identical), KRT76 (64% identical), KRT1 (64% identical), KRT2 (61% identical), KRT4 (59% identical), KRT79 (58% identical), KRT77 (56% identical), KRT73 (53% identical), and 56 more.
Diseases named in the same sentence as KRT5 in open-access papers:
KRT5 is named in the same sentence as 319 diseases in open-access papers, as found by Europe PMC text mining. Sharing a sentence is not in itself a finding about the gene and the disease. The quoted sentences say what the papers report.
breast carcinoma (322 papers, 2006 to 2025). "For example, it has been shown that KRT17 and KRT5 were significantly upregulated in basal-like breast carcinomas, and the overexpression of KRT17 was associated with poor prognosis of cancer." (PMID 37468850, 2023). "Previous research has confirmed that keratin 5 is a stem cell marker in breast cancer and is associated with cancer recurrence and chemotherapy resistance in ovarian cancer." (PMID 35054979, 2022). "Analysis of 507 ER-negative and 1,356 ER-positive breast cancer patients revealed that keratin-5 associated with ER-negative breast cancers in seven out of 13 datasets, and that Notch-1 associated with ER-negative breast cancers in nine out of 16 datasets." (PMID 19025652, 2008). "Based on our recent data, we focused on survivin – a mitotic regulator and cell death inhibitor overexpressed in breast cancer, and associated with unfavorable outcome – and keratin-5 – a marker of basal epithelium, often linked to a progenitor/stem cell phenotype." (PMID 19025652, 2008). "KRT5 is a well-established basal/myoepithelial marker in breast cancer, enriched in basal-like and triple-negative subtypes, where its upregulation has been associated with aggressive phenotypes, chemoresistance, and poorer survival outcomes." (PMID 41194133, 2025). "Gene expression studies have previously identified KRT5 mRNA in normal breast and basal-like breast cancer, and monoclonal antibodies against KRT5 have been used to identify basal-like TNBC." (PMID 36536459, 2022). "In a spontaneous Wsh-MMTV-PyMT breast cancer model, mast cell absence delayed onset of cytokeratin 5+ basal-like breast cancers." (PMID 33922465, 2021). "Because human breast cancer shows disruption in the myoepithelial layer, we immunostained cells for the myoepithelial cell markers cytokeratin 5 (CK5) and p63." (PMID 31978754, 2020). "Previously, we have shown that miR-18a and miR-18b gene expression strongly correlates with high proliferation, oestrogen receptor -negativity (ER−), cytokeratin 5/6 positivity and basal-like features of breast cancer." (PMID 32370743, 2020). "Hierarchical clustering of NCS‐1 and breast cancer molecular markers showed a positive correlation with basal and proliferative markers, such as KRT5, 14 and 17, CDH3, FOXC1, FOXM1, EGFR, and MKI67." (PMID 31647602, 2020). "Both primary and passaged tumors expressed similar levels of both Keratin 5 and Keratin 8/18, as is observed in basal-like breast cancer." (PMID 30484104, 2019). "Basal-like breast cancer (BLBC) is a subtype of breast cancer defined by gene expression profiling and it is characterised by the expression of genes related to basal epithelial cells such as keratin 5, keratin 17, integrin-β4 and laminin." (PMID 29380207, 2018). "In the dataset of 50 breast cancer lines TF expression clustered with higher levels of basal-marker vimentin, keratin KRT5/14 and caveolin-1 (CAV1) but lower levels of luminal-marker keratin KRT8/18, ERBB3 and ESR1." (PMID 28938620, 2017). "Breast cancer specimens that expressed keratin 8/18, markers of luminal epithelial cells, were classified as luminal breast cancers, while those that expressed keratin 5/6, markers of basal epithelial cells, were classified as basal breast cancer." (PMID 27918430, 2016). "In breast cancer, several lines of evidence have implicated overexpression of EZH2 and repression of tumor suppressors such as KRT5, KRT6, CDH3, RAD51 paralogs, CDKN1C, FOXC1, Wnt/β-catenin signaling (c-Myc, Cyclin D1, Axin2), RKIP and KLF2." (PMID 27835578, 2016).
breast carcinoma (continued). "The measurement of tumoral miR-548c-5p expression levels in combination with three conventional breast cancer prognostic factors (node invasion, tumor size and cytokeratin 5/6 expression), allowed for the relapse prediction of patients with an AUC = 0.96." (PMID 26490435, 2015). "We examined the cytokeratin 5 (CK5) expression level in the MCF-7 sublines since CK5 has been detected in an ER−/PR− subpopulation of the ER+ T47D breast cancer cell line." (PMID 24724101, 2014). "We compared expression of cytokeratin 5, 14 and 17 in 115 patients with operable breast cancer estimated by real-time RT-PCR and immunohistochemistry." (PMID 20426817, 2010). "Gene expression microarray analysis showed that KB1P tumors expressed markers of basal-like breast cancer, for example p63 and keratin 5, compared with the KP tumors." (PMID 19709408, 2009). "A total of 42 cases of male breast carcinoma were examined retrospectively using immunostains for estrogen receptor (ER), progesterone receptor (PR), cytokeratin 5/6 (CK5/6), EGFR, and NF-κB." (PMID 19442295, 2009). "Pooled estimates of Pearson's correlation coefficient between Notch-1/keratin-5 were 0.3315 and 0.2043 for ER-negative and ER-positive breast cancers, respectively (P = 0.04)." (PMID 19025652, 2008). "Cytokeratin 5 and 17 have also been found in a subset of breast cancer and identified patients with poor clinical outcome." (PMID 17389037, 2007). "In comparison with those consistently classified as basal-like (n = 46), the tumors clustered as ERBB2 (n = 12) showed a lower average expression in KRT17, KRT5 and especially GABRP, which has been reported to be associated with ER-/HER2- breast cancers." (PMID 16846532, 2006). "Similarly, unipotent Krt5 and Lgr5 expressing cells in these studies were also described to form mammary tumors (mostly adenomyoepitheliomas) upon Pik3caH1047R expression, composed of both epithelial cell types revealed by lineage tracing." (PMID 40676433, 2025). "Also, PRL was found to suppress induction of the cytokeratin-5 (CK5)-positive stem-like population in breast cancer cells both in vitro and in vivo." (PMID 36157462, 2022). "Furthermore, the expression of several cytokeratin genes such as KRT5, KRT6B, KRT14, and KRT17 was associated with basal-like breast cancer, a breast cancer subtype that is highly associated with poor treatment outcome." (PMID 35911770, 2022). "Furthermore, KRT5 expression induced by progestins was sufficient to promote cell junction reconstruction and cell morphology remodeling in breast cancer." (PMID 34659370, 2021). "Notably, all the cancer cells from the four models showed high Krt18 expression, and only some cells from the BRCA1 model, a basal-like breast cancer model, showed a detectable Krt5 transcript." (PMID 34497807, 2021). "While the results of combinatorial therapeutic strategies with retinoids in patients with breast cancer have been generally disappointing, retinoids have been shown to inhibit the expansion of chemoresistant cytokeratin 5-positive (CK5+) cells through RAR/PR crosstalk." (PMID 34638457, 2021). "Actually, in a breast cancer cell line (MCF7) transfected with plasmid carrying DDD mutation in KRT5, K5 was not embodied in cytoskeletal intermediate filament network persisting in its soluble form." (PMID 32545758, 2020). "In canine mammary carcinomas, loss of HER2 expression has been associated with a poor prognosis in combination with ER-negative status and positivity of basal cell markers (P-cadherin, p63, cytokeratin 5)." (PMID 33282730, 2020). "The putative CTCs cultures exhibited cellular markers associated with breast cancers (cytokeratin 5, cytokeratin 8, and mammaglobin), but are lacking in red blood cells which would be the only plausible contaminant." (PMID 32998338, 2020).
breast carcinoma (continued). "The MD Anderson Cancer Center (MDACC) subtypes resembled those identified for breast cancer and showed typical mRNA expression profiles of basal and luminal markers, with keratin 5 (KRT5) expression being highly upregulated in basal and keratin 20 (KRT20) being upregulated in luminal tumors." (PMID 30380731, 2018). "The aim of this study was to screen the male patients with breast cancer for BRCA mutations as well as tissue markers of estrogen receptor (ER), progesterone receptor (PR), human epidermal growth factor receptor (HER-2) and cytokeratin 5/6 (CK5/6)." (PMID 27478808, 2016). "In contrast, basal-like breast cancers express no hormonal receptors, are cytokeratin 5/6 or 14 positive, associated with poor prognosis and constitute 14–20% of all breast cancer cases." (PMID 23144930, 2012). "A total of 44 human breast cancer cell lines and three immortalized breast epithelial lines were categorized as representing luminal or basal breast cancer subtypes based on the relative gene expression of cytokeratin 8/cytokeratin 18 and cytokeratin 5/cytokeratin 17, respectively." (PMID 19874578, 2009). "It has long been speculated that basal-like breast cancers originate from a basal cell-of-origin as the resulting tumor lacks steroid hormone receptors and expresses specific markers restricted to the normal basal cells, such as αSMA, KRT5 or KRT14." (PMID 40676433, 2025). "The triple negative/basal-like (TN/BL) breast cancer subtype comprises ∼15% of all breast cancers and is defined as estrogen (ERα)-, progesterone (PR)- and HER2- (not amplified) receptor negativity, but basal-associated markers- (e.g., cytokeratin 5/6 and 17) positivity." (PMID 22511931, 2012). "Using a combination of these markers, 60 HR+/HER2+ breast cancer patients were classified into the following subtypes: (a) IHC-III: CD8A+; (b) IHC-IV: CD8A− and KRT5+; (c) IHC-II: CD8A−, KRT5− and GFRA1+; (d) IHC-I: CD8A−, KRT5−, GFRA1− and PFKP+." (PMID 40133264, 2025). "Keratin 5 (KRT5) is a member of the keratin family, highly expressed in basal-like breast cancer and commonly used as a marker for basal-like subtype identification." (PMID 40612672, 2025). "The expression levels of VIM, KRT5 and KRT17 in normal samples were significantly higher than those in breast cancer samples." (PMID 38581422, 2024). "Cluster III, termed basal/squamous, was characterised by squamous histology and KRT5/KRT14 expression, similar to the basal-like profile in breast cancer." (PMID 39594166, 2024). "To investigate potential epigenetic regulation of KRT5/6A/6B and KRT14/16/17, we first compared their regional epigenetic landscapes on chromosome 12 and 17, respectively, in luminal and basal breast cancer cell lines and tumors." (PMID 35440136, 2022). "We observed that tumor cells in this model showed varying expression levels of luminal cell markers (cytokeratins 8/18 and 19), basal cell markers (cytokeratin 5 and SMA) and other breast cancer epithelial markers such as HER2 and CD44." (PMID 35121992, 2022). "While BUB1, KRT5, and MYCN were overexpressed in young women with breast cancer, CXCL12 showed a decreased expression." (PMID 36685821, 2022). "KRT14-expressing breast cancer cells were shown to lead the collective invasion process and to activate a basal gene program, which included TP63 and KRT5, needed for the initial phases of metastasis in breast cancer cells." (PMID 35187501, 2021). "Basal-like breast cancers are characterized by ER−, PR−, HER2−, cytokeratin 5/6 (CK5/6)+ and expression of epidermal growth factor receptor (EGFR)." (PMID 29484537, 2018). "Classification of primary breast cancer RNASeq data based on high/low CEBPB/REST/CTCF revealed that, KRT5, KRT14 and KRT17 mRNAs were significantly upregulated in CEBPBhigh and CTCFlow tumors." (PMID 30335837, 2018).
breast carcinoma (continued). "Gene expression profiling defines basal breast cancers as those exhibiting basal clusters of genes that include EGFR, basal cytokeratin 5/6, C–kit, proliferation cluster and low expression of Her2neu and hormone receptor related genes." (PMID 29884220, 2018). "KRT5 combines with transforming growth factor beta receptor 3 (TGFBR3) and transcription factor JunD to promote breast cancer cell growth." (PMID 29069744, 2017). "To characterize the expression of AXL in vitro, we analyzed the expression of the tyrosine kinase, EMT (CDH1 and VIM), and basal (EGFR, KRT5, and KRT6A) markers in 15 breast cancer cell lines by quantitative real-time PCR (qRT-PCR)." (PMID 28721387, 2016). "Instead, five protein markers - ER, PR, HER2, Cytokeratin 5 (CK5) and epidermal growth factor receptor-1 (EGFR) - can serve as surrogates to classify breast cancers into subtypes analogous to those defined by gene profiling." (PMID 25116921, 2014). "Cheang reported that the expanded surrogate of PgR, HER2, EGFR, and cytokeratin 5/6 indicate a more specific definition of basal-like breast cancer, mostly TNBC, which better predicts breast cancer survival." (PMID 19534825, 2009). "KRT5/KRT18, for example, are dysregulated in cancers originating from basal epithelial cells, playing a role in epithelial-mesenchymal transition (EMT) in basal-like cancers such as breast cancer." (PMID 40722520, 2025). "When stained for Krt5, a basal marker used to identify basal-like breast cancer subtypes, none of the luminal B samples expressed Krt5, but 65% of the low-ER samples were Krt5+." (PMID 36859337, 2023). "KLF5 was coexpressed with basal markers (KRT5, KRT14 and KRT17) in breast cancer tissue." (PMID 36923542, 2023). "In breast carcinoma, NUCKS1 exhibited higher expression than other investigated markers (including Ki67, estrogen receptor, progesterone receptor, human epidermal growth factor receptor 2, and cytokeratin 5/6)." (PMID 35069784, 2022). "Moreover, the simple subtype showing the highest correlation in TNBC expressed KRT5 and MKI67, which has been known and used as immunohistochemical markers for basal-like breast cancer and proliferation." (PMID 30205506, 2018). "Cheang MC put forward that the special type (ER−/PR−/HER2−/cytokeratin 5+ and/or EGFR+) of basal-like breast cancers might have cancer stem-like properties and the strong tendency to metastasize early." (PMID 29088770, 2017). "We found that TF expression in breast cancer lines and tumors closely clustered with higher levels of EMT (high vimentin/low E-cadherin) and classical basal-type biomarkers KRT5, KRT14 and caveolin-1, while it clustered with lower levels luminal-type biomarkers KRT8, KRT18, ERBB3 and ESR1." (PMID 28938620, 2017). "Two of the 3 LAR models were KRT5 and KRT17 negative at the protein level, Vimentin was highly expressed in 2 out of 3 metaplastic breast cancer, which also showed loss of E-cadherin expression." (PMID 27374081, 2016). "The basal-like breast cancer is IHC characterized by overexpression of cytokeratin 5/6/14 and epidermal growth factor receptor and lack of expression of ER, PR and HER2." (PMID 24731479, 2014). "Moreover, the x43 cells represent a basal-like breast cancer as they express EGFR, Keratin 5 and Keratin 6A." (PMID 23593654, 2013). "Clinically, basal-like breast cancer is characterized as the triple-negative phenotype (ER, PR, HER2, all negative) and as resembling stem-like cells, composed mainly of cells expressing the cancer stem cell markers CD44+ and cytokeratin 5/6." (PMID 19589136, 2009).